ARL5B (ARF like GTPase 5B)
Description:
Binds and exchanges GTP and GDP.
Synonyms: ARL8
Tractability: Small molecule: a structure with a bound ligand is known. PROTAC: ubiquitination databases record sites on it; its protein half-life has been measured.
Gene: Protein-coding gene on chromosome 10 (18,659,304 to 18,681,639, forward strand). Ensembl gene ENSG00000165997.
Gene Ontology:
Molecular function: protein binding; GTP binding; GTPase activity
Biological process: protein localization to Golgi membrane; intracellular protein transport
Cellular component: trans-Golgi network
Genetic constraint (gnomAD): Loss-of-function variants: 5 observed, 18.37 expected, observed/expected ratio (o/e) 0.27, 90% interval 0.14 to 0.57. The upper end of that interval is the gene's LOEUF score, 0.57, which puts it in group 2 of 6, group 1 being the genes least tolerant of losing a copy. Missense variants: 124 observed, 163.21 expected, observed/expected ratio (o/e) 0.76, 90% interval 0.66 to 0.88. Synonymous variants: 66 observed, 54.11 expected, observed/expected ratio (o/e) 1.22, 90% interval 1 to 1.5.
Homologues: Orthologues: chimpanzee ARL5B (100% identical), macaque ARL5B (100% identical), mouse Arl5b (100% identical), pig ARL5B (100% identical), rabbit ARL5B (100% identical), rat Arl5b (99% identical), zebrafish arl8 (96% identical), dog ARL5B (92% identical), guinea pig ARL5B (91% identical), tropical clawed frog arl5b (83% identical), Drosophila melanogaster Arl5 (71% identical). Paralogues in human: ARL5A (80% identical), ARL5C (68% identical), ARF1 (51% identical), ARF3 (49% identical), ARL1 (48% identical), ARF4 (44% identical), ARF5 (44% identical), ARF6 (42% identical), ARL3 (42% identical), TRIM23 (41% identical), ARL2 (41% identical), ARL4A (40% identical), and 18 more.
Diseases named in the same sentence as ARL5B in open-access papers:
ARL5B is named in the same sentence as 27 diseases in open-access papers, as found by Europe PMC text mining. Sharing a sentence is not in itself a finding about the gene and the disease. The quoted sentences say what the papers report.
breast carcinoma (9 papers, 2021 to 2025). "Functional studies revealed that FTO promoted breast cancer progression by affecting miR-181b-3p/ARL5B signaling and directly regulating the m6A methylation of 3′UTR of BNIP3 mRNA." (PMID 40002690, 2025). "Previous research has indicated that ARL5B augmented the translocation and infiltration of breast cancer cells, suggesting its oncogenic function in breast cancer." (PMID 40027133, 2025). "In both cell lines, the most significantly downregulated gene, ARL5B, along with its downstream lysosomal trafficking, was believed to be closely related to the proliferation of various tumors, including ovarian and breast cancers." (PMID 41451209, 2025). "Previous reports showed that the upregulation of FTO enhanced cell migration and invasion by affecting the miR-181b-3p (microRNAs, miRNAs)/ARL5B signaling pathway in breast cancer." (PMID 38782769, 2024). "Recently, FTO was discovered to increase the expression of ADP ribosylation factors like GTPase 5B (ARL5B) in breast cancer cells by inhibiting miR-181b-3p." (PMID 36553003, 2022). "For example, FTO can regulate the migration and invasion of breast cancer cells by regulating the FTO/Mir-181B-3P/ARL5B signaling pathway, which ultimately affects the development of breast cancer." (PMID 34660577, 2021). "The FTO/miR-181b-3p/ARL5B axis modulates the migration and invasion of breast cancer cells." (PMID 36553003, 2022). "Moreover, studies have indicated that ARL5B may enhance the migratory and invasive capabilities of breast cancer cells by accelerating lysosomal redistribution to the cell periphery." (PMID 41451209, 2025). "Furthermore some researchers believe that FTO primarily stimulates the oncogenic activity of breast cancer cell invasion and migration through the FTO/miR-181b-3p/ARL5B signaling pathway, promoting tumor proliferation." (PMID 35707365, 2022).
ovarian carcinoma (3 papers, 2021 to 2025). A malignant neoplasm originating from the surface ovarian epithelium. "In present study, we found ARL5B level in ovarian cancer tissue samples was higher than in normal ovarian tissue samples." (PMID 33419459, 2021). "Collectively, These in vivo findings coincide with the in vitro changes observed in the cell models, showing that miR-145 inhibited ARL5B expression in ovarian cancer." (PMID 33419459, 2021). "Futhermore, miR-145 overexpression decreased ARL5B expression in ovarian cancer tissue subcutaneous tumors of nude mice." (PMID 33419459, 2021). "highlighted that targeting ARL5B can inhibit the mitochondrial function of ovarian cancer cells, which affects the metabolic reprogramming of tumor cells and consequently inhibits tumor growth, invasion, and metastasis in ovarian cancer." (PMID 41451209, 2025). "In order to investigate whether miR-145 inhibited mitochondrial function by targeting ARL5B in ovarian cancer cells, we confirmed the mtDNA copy number, ATP production, and mitochondrial activity in different groups." (PMID 33419459, 2021). "Moreover, by comparing the relationship between RNA expression levels of miR-145 and ARL5B in ovarian cancer tissue samples, we found that the mRNA expression of ARL5B was negatively correlated with miR-145 in ovarian cancer tissue samples." (PMID 33419459, 2021). "However, the role of ARL5B in ovarian cancer remains unclear." (PMID 33419459, 2021).
prostate carcinoma (3 papers, 2021 to 2025). A carcinoma that arises from epithelial cells of the prostate gland. "ARL5B silencing reduced lysosome dispersion and subsequently decreased cell invasion in prostate cancer." (PMID 33419459, 2021). "Furthermore, suppression of ARL5B resulted in a decrease in the scattering of lysosomes and subsequently led to a reduction in cell invasion in prostate cancer." (PMID 40027133, 2025).
viral infection (2 papers, 2018 to 2024). "Since ARL5b controls traffic between endosomes and the Trans Golgi Network, we then hypothesized that ARL5b overexpression could participate in the membrane fluxes induced by the viral infection." (PMID 38332148, 2024).
depressive disorder (1 paper, 2022). A melancholy feeling of sadness and despair. "Several of the SNVs assigned to CTCF and CACNB2 have potential functional consequences, and a gene in close proximity to CACNB2, i.e., ARL5B, was identified as a potential gene of interest in schizophrenia and depressive disorder comorbidity." (PMID 35328011, 2022).
esophageal carcinoma (1 paper, 2026). A primary or metastatic malignant neoplasm involving the esophagus. "Bioinformatic analysis based on the Cancer Genome Atlas (TCGA) database initially revealed a significant association between ARL5B expression and multiple malignancies, including esophageal carcinoma (ESCA), rectum adenocarcinoma (READ), thymoma (THYM), stomach adenocarcinoma (STAD)." (PMID 41144804, 2026).
major depressive disorder (1 paper, 2023). An episode of depression lasting two or more weeks without an intervening episode of mania. "For example, the ARL5B gene that is the top-ranked gene in terms of importance in our analysis, found to be significant in about two thirds of all models, has been reported to be connected to suicide attempts in major depressive disorder." (PMID 37680967, 2023).
non-small cell lung carcinoma (1 paper, 2025). A group of at least three distinct histological types of lung cancer, including non-small cell squamous cell carcinoma, adenocarcinoma, and large cell carcinoma. "further indicated that in non-small cell lung cancer, ARL5B is essential for inhibiting cell proliferation, invasion, and mitochondrial function, while promoting apoptosis signaling pathways." (PMID 41451209, 2025).
retinoblastoma (1 paper, 2025). A malignant tumor that originates in the nuclear layer of the retina. "In summary, we presented in vivo and in vitro evidence that ARL5B, which is highly expressed in retinoblastoma, promotes cell migration via the ARL5B/SKIP/Kinesin-1 signaling pathway." (PMID 41451209, 2025). "RPL41 down-regulates the expression of ARL5B by degrading ATF4 and the impaired ARL5B-related lysosomal trafficking is a mechanism to inhibit the metastasis of retinoblastoma." (PMID 41451209, 2025). "We utilized quantitative real-time PCR (qRT-PCR), Western blotting, and immunohistochemistry to assess the expression levels of ARL5B(ADP ribosylation factor like GTPase 5B) in retinoblastoma cell lines and tissues." (PMID 41451209, 2025). "Based on this, we selected the ARL5B gene as the focus of subsequent research to further explore the therapeutic mechanisms of RPL41 in retinoblastoma." (PMID 41451209, 2025). "ARL5B was upregulated in retinoblastoma cells and clinicopathological tissues." (PMID 41451209, 2025). "Furthermore, overexpression of ARL5B was shown to promote the migration of retinoblastoma cells and partially counteract the inhibitory effects of RPL41 on these cells." (PMID 41451209, 2025). "We initially investigated the expression levels of ARL5B in retinoblastoma tissues." (PMID 41451209, 2025). "Additionally, ARL5B has been validated as a downstream target gene regulated by the transcription factor ATF4 in retinoblastoma." (PMID 41451209, 2025). "Therefore, it could be concluded that RPL41 may exert its inhibitory effect on retinoblastoma by modulating the ARL5B/SKIP/Kinesin-1 pathway." (PMID 41451209, 2025). "Therefore, we hypothesized that RPL41 may influence the growth of retinoblastoma cells by downregulating ARL5B." (PMID 41451209, 2025). "In this study, we investigated the expression and function of ARL5B in retinoblastoma and further explored the underlying mechanisms, providing an experimental basis for the clinical application of RPL41 and identifying a new target for the treatment of retinoblastoma." (PMID 41451209, 2025). "RPL41 inhibits the lysosomal trafficking of the ARL5B/SKIP/Kinesin-1 signaling pathway by promoting the degradation of ATF4, thereby suppressing the growth and metastasis of retinoblastoma." (PMID 41451209, 2025). "Initial observations from clinical retinoblastoma pathological sections revealed a consistent expression trend, wherein the levels of ATF4 and ARL5B were both lower in normal para-cancerous retinal tissues compared to RB tumor tissues." (PMID 41451209, 2025). "Notably, ARL5B is highly expressed in retinoblastoma, and the activity of the ARL5B/SKIP/Kinesin-1 lysosomal trafficking facilitates the growth and metastasis of retinoblastoma." (PMID 41451209, 2025).
cancer (5 papers, 2020 to 2026). A tumor composed of atypical neoplastic, often pleomorphic cells that invade other tissues. "Although existing literature suggests ARL5B‐driven metabolic alterations in other malignancies, its direct involvement in lipid metabolism, a core adaptive mechanism in cancer, remains uninvestigated." (PMID 41144804, 2026). "As a member of the ARF family, which regulates tumorigenesis across multiple cancer types, ARL5B is identified here as an oncogenic driver in ESCC." (PMID 41144804, 2026). "Through the Cancer Genome Atlas (TCGA) pan‐cancer analysis, ARL5B is initially identified as a promising candidate gene, correlating with advanced tumor, node, metastasis (TNM) stages and poor survival." (PMID 41144804, 2026). "Among them, FTO promotes the metastasis and invasion of cancer cells through the FTO/miR-181b-3p/ARL5B signaling pathway." (PMID 36561529, 2022). "Given ARL5B overexpression in ESCC, we next assessed its functional impact on cancer cell proliferation." (PMID 41144804, 2026).
tumor (5 papers, 2021 to 2026). "Genes associated with ARL5B and lysosome transport pathways in vitro are closely linked to tumor invasion." (PMID 41451209, 2025). "Comparative analysis of 182 ESCA specimens and 286 adjacent normal esophageal epithelial tissues demonstrated a marked upregulation of ARL5B messenger RNA (mRNA) levels in tumor tissues (p < 0.05), implicating ARL5B as a potential oncogenic driver in ESCA." (PMID 41144804, 2026). "Collectively, these data reveal that ARL5B drives lipid synthesis and tumor progression via ROCK1‐mediated activation of SREBP1, providing mechanistic insights into how metabolic alterations fuel ESCC aggressiveness." (PMID 41144804, 2026). "By terminal sacrifice, tumors from the shARL5B group displayed significantly decreased tumor volume and mass compared to controls (both p < 0.001), with ARL5B protein levels in tumor tissues confirming effective knockdown between the two groups (p < 0.05)." (PMID 41144804, 2026). "In contrast, fatostatin hydrobromide treatment substantially suppressed tumor growth in ARL5B‐OE xenografts (p < 0.001)." (PMID 41144804, 2026). "Beyond elucidating ARL5B's pivotal role in tumor lipid metabolism, our findings establish a theoretical framework for targeting this pathway and propose ARL5B as a potential therapeutic vulnerability for metabolic intervention strategies in ESCC." (PMID 41144804, 2026). "Clinical correlation further demonstrated that elevated ARL5B expression correlated with advanced tumor progression and inferior survival, supporting a functional role in ESCC pathogenesis." (PMID 41144804, 2026). "Lentiviral‐mediated ARL5B knockdown (shARL5B_1) in KYSE150 cells significantly attenuated tumor growth kinetics in BALB/c nude mice." (PMID 41144804, 2026). "Two limitations merit attention: current models incompletely recapitulate tumor microenvironment‐mediated lipid metabolism remodeling, and specific ARL5B inhibitors remain unavailable for therapeutic validation." (PMID 41144804, 2026). "The reversal of both lipid accumulation and tumor growth upon SREBP1 inhibition solidifies its role as the critical downstream effector mediating ARL5B's oncogenic functions." (PMID 41144804, 2026). "Immunoblotting assays of 12 paired ESCC tumor and normal tissue samples demonstrated significantly elevated ARL5B protein levels in tumor tissues relative to normal counterparts." (PMID 41144804, 2026). "The transport process dependent on ARL5B can promote lysosomal exocytosis, releasing tissue cathepsins and other proteases into the tumor microenvironment (TME)." (PMID 41451209, 2025). "In BRCA, FTO facilitates tumor cell migration and invasion by upregulating ADP ribosylation factor-like GTPase 5B (ARL5B) through demethylating the miR-181b-3p." (PMID 35804965, 2022). "In vitro experiments have similarly shown that FTO is a tumor-promoting factor that activates miR-181b-3p/ARL5B signaling leading to tumor migration." (PMID 36035182, 2022). "ARL5B expression exhibited a stepwise elevation across tumor stages (H‐score analysis, normal tissue vs stage I, p < 0.05; stage I vs stage II, p < 0.01; stage I vs stage III, p < 0.001; stage I vs stage IV, p < 0.001), with stage IV lesions showing the most intense staining (right)." (PMID 41144804, 2026). "These include proteins involved in vesicle transport, such as Rab10, a pathway closely linked to ARL5B-mediated lysosomal trafficking, as well as ELOVL5(elovl fatty acid elongase 5), which has been implicated in tumor immunity through immunometabolic regulation." (PMID 41451209, 2025). "In this study, we propose that ATF4 may promote tumor growth and metastasis by activating the expression of ARL5B, thereby influencing the SKIP/Kinesin-1 pathway." (PMID 41451209, 2025). "Therefore, RPL41 may reduce protease release and maintain the chemokine gradient by inhibiting ARL5B-mediated lysosomal exocytosis, thereby promoting the recruitment of anti-tumor immune cells." (PMID 41451209, 2025).
tumor (continued). "This study pioneers the systematic elucidation of ARL5B's overexpression in ESCC through clinical specimen and cellular model analyses, and evaluates its functional contributions to tumor progression to address this scientific void." (PMID 41144804, 2026). "Lysosomes move along microtubules toward the cell periphery in an ARL5B/SKIP/Kinesin-1 pathway-dependent manner, which is critical for tumor cell migration." (PMID 41451209, 2025). "The results of the in vivo tumorigenesis experiments demonstrated that RPL41 inhibits tumor growth and slows the progression of RB by suppressing the expression of ATF4 and ARL5B in RB cells." (PMID 41451209, 2025). "Consistent with the previous verification, immunohistochemical staining of tumor tissues harvested from nude mice revealed that RPL41 treatment led to decreased expression levels of ATF4 and ARL5B in RB tissue, suggesting that RPL41 could inhibit the expression of these proteins." (PMID 41451209, 2025).
infection (1 paper, 2024). The state of being infected such as from the introduction of a foreign agent such as serum, vaccine, antigenic substance or organism. "Therefore, we can also hypothesize that the difference of ARL5b regulation between these cells could be linked to the permissiveness of the cells to the infection." (PMID 38332148, 2024). "Upon HRV16 infection, a decrease of ARL5b mRNA expression was observed as early as 4 h post infection and onwards." (PMID 38332148, 2024). "The unbiased approach using RNA sequencing of HRV-infected macrophages allowed us to identify one potential gene related to transport from and to the TGN, the small GTPase ARL5b, which was upregulated after infection." (PMID 38332148, 2024). "This indicates that HRV16 infection leads to inhibition of ARL5b expression." (PMID 38332148, 2024). "However, in HeLa Ohio cells, ARL5b expression is decreased by the infection." (PMID 38332148, 2024). "This highlights that in permissive cells, overexpression of ARL5b limits the secretion of HRV16 virions and thus the propagation of the infection." (PMID 38332148, 2024). "We also show that ARL5b inhibits HRV16 secretion in permissive cells, and therefore we identified ARL5b as a novel restriction factor of HRV16 infection in this context." (PMID 38332148, 2024). "Interestingly, in these epithelial cells, ARL5b expression was not modified from 0 h to 96 h post infection and increased at 120 h post infection." (PMID 38332148, 2024). "This hypothesis is strengthened by our results in the non-permissive epithelial cell line BEAS-2B, in which ARL5b expression was increased at late time points post infection and in which HRV16 does not replicate." (PMID 38332148, 2024).
ARL5B also shares sentences with these, for which no sentence is quoted: esophageal squamous cell carcinoma (2 papers); Parkinson disease (2); Alzheimer disease (1); diabetic retinopathy (1); Hypertension (1); influenza (1); neurodegenerative disease (1); Niemann-Pick disease type C (1); rectum adenocarcinoma (1); retinal degeneration (1); Salmonella Infections (1); schizophrenia (1); stomach adenocarcinoma (1); sudden cardiac arrest (1); thymoma (1).